TMEM191A (transmembrane protein 191A (pseudogene))
Synonyms: DKFZp434N035; TMEM191AP
Gene: Transcribed unprocessed pseudogene on chromosome 22 (20,702,007 to 20,704,490, forward strand). Ensembl gene ENSG00000226287.
Subcellular location: Membrane
Diseases named in the same sentence as TMEM191A in open-access papers:
TMEM191A is named in the same sentence as 2 diseases in open-access papers, as found by Europe PMC text mining. Sharing a sentence is not in itself a finding about the gene and the disease.
TMEM191A shares sentences with these, for which no sentence is quoted: cancer (1 paper); diabetes (1).